CXCR4 (C-X-C motif chemokine receptor 4)
Diseases named in the same sentence as CXCR4 in open-access papers (continued):
Sharing a sentence is not in itself a finding about the gene and the disease.
tumor (continued). "As formation of primary tumors with a volume of 5-25 mm3 required two weeks, treatment with the CXCR4 inhibitor started at day 14 after tumor inoculation." (PMID 27835905, 2016). "The use of CXCR4 antagonists as a therapeutic targeted approach to inhibit tumor spreading and the formation of metastases has been introduced in clinical trials for different cancer types." (PMID 26744352, 2016). "Consistently with previous reports, we were able to distinguish among both LLC and B16 tumor minor subpopulations with CXCR4 expression that is thought to characterize cancer stem cells." (PMID 26385771, 2016). "To phenocopy the suppressive effect of CXCR4 pharmacological inhibition on tumor aggressiveness, we used RNA interference." (PMID 26744352, 2016). "SDF-1 elicits its effect through its specific CXC chemokine receptor (CXCR4), which is known to play roles in tumor metastasis and chemotherapy resistance." (PMID 27668882, 2016). "Microenvironment conditions such as hypoxia induce CXCR4 expression which further sensitizes tumor cells to signals such as CXCL12 and promotes tumor metastasis." (PMID 26884752, 2016). "In MSCs, activated RAGE triggers CXCR4 expression leading to directed migration of MSCs towards SDF1-secreting GemOE/TNBC cells in tumor cores." (PMID 26989079, 2016). "In particular, exposure of tumor cells to microenvironmental stress, including growth factor deprivation, hypoxia, and physical growth constraints resulted in upregulation of CXCR4, either at the level of mRNA or cell surface protein expression, or both." (PMID 27528222, 2016). "The tumor suppressing role of USP33 is at least partially dependent on β-arrestin-mediated ERK signaling downstream of SDF-1/CXCR4, demonstrating the prospect of deubiquitinating enzyme modulator and biased-ligand development of GPCRs in cancer therapy." (PMID 27835898, 2016). "Since both HSCs and PC cells use the CXCL12/CXCR4 axis for occupying the osteoblastic niche, plerixafor inhibited CXCL12/CXCR4 interactions, leading to reduced tumor growth when given at the time of tumor implantation." (PMID 27809841, 2016). "In CRC, it has been shown in clinical studies that CXCR4 expression correlates with tumor recurrence, poor survival and liver metastasis." (PMID 27136535, 2016). "Proliferative and pro-survival signaling pathways can be induced by activation of CXCR4 on the surface of tumor cells, and blocking the CXCR4 receptor, accordingly, results in inhibition of tumor proliferation." (PMID 27307990, 2016). "From this study, it is evident that GNG4 is a tumor suppressor in GBM which functions by abrogating the migration property of GBM cells through inhibition of mainly the ERK pathway downstream to CXCR4/SDF1α signaling axis." (PMID 27382437, 2016). "The diagnostic accuracy of CXCR4 was similar to CRP, much higher than that for CXCL12 and classical tumor markers and increased to 77% in combination with CRP." (PMID 27041792, 2016). "Mice were treated every third day with CXCR4-mAb, control-mAb or vehicle (saline), at a dose of 10 mg/kg, and tumor growth was measured." (PMID 26848769, 2016). "Final tumor volumes were also equivalent between the groups at the time of necropsy, with a trend to increased volume in CXCR4 positive cell-derived tumors." (PMID 27528222, 2016). "Blocking CXCR4 on tumor cells with AMD3100 in-vitro, inhibits migration of GL26-Cit and HF2303 toward MBVE and HBMVE cells." (PMID 27863376, 2016). "SUM149 tumor weights from CXCR4-mAb treated mice were 23.6±0.3% and 31.9±0.4% lower compared to control-mAb and vehicle groups, respectively." (PMID 26848769, 2016). "As angiogenesis is also crucial for tumor metastasis, the mRNA expressions of metastasis-related molecules CXCR4 and AKT were also examined in tumors." (PMID 27731376, 2016). "The report indicated that a subpopulation of migrating CD133+ CXCR4+ cancer stem cells was essential for tumor metastasis." (PMID 27175473, 2016).
tumor (continued). "A rapid accumulation of T-cells in the tumour was observed when CXCR4 was inhibited, thus restoring the ability of the immune system to eliminate the cancer cells." (PMID 27542276, 2016). "According to the results, the SDF1α -CXCR4 signaling pathway plays a major role in the tumor specific migration of commonly used stem cell types, including mesenchymal SCs, embryonic SCs and induced pluripotent SCs." (PMID 27494901, 2016). "H1155 tumor weights from CXCR4-mAb treated mice were 60.0 ± 8.3% lower compared to the control-mAb and vehicle treated groups." (PMID 26848769, 2016). "Our study demonstrated that the tumor-promoting activity of RUNX2 was attributable to its transcriptional up-regulation of the chemokine receptor CXCR4, which has been shown to mediate the invasion and metastasis of a variety of cancers." (PMID 27007162, 2016). "The results were consistent with the in vitro observation that CXCR4 antibody LY2624587 induced apoptosis in multiple tumor cells including CCRF-CEM cells." (PMID 26954567, 2016). "Our findings show that CXCR4 down-regulated cells (GL26-Cit-sh2CXCR4) are less invasive even from early stages of tumor growth." (PMID 27863376, 2016). "Although CXCR4 mRNA was increased in SKCXCR2-derived tumor tissues, its enhanced levels were still low." (PMID 27723802, 2016). "On the other hand, tumor borders of mice implanted with low CXCR4 expressing GL26-Cit-sh2CXCR4 cells were less invasive." (PMID 27863376, 2016). "Across large datasets, decreased GRK3 expression correlated better with tumor (vs normal breast) than changes in CXCR4 expression." (PMID 27049755, 2016). "Taken together, PAUF is correlated with the promotion of MDSC recruitment to tumor tissues, possibly via the upregulation of CXCR4." (PMID 27322081, 2016). "Among them, lymphatic endothelial cells secrete chemokines such as CXCL12 that can promote tumor cells expressing the cognate receptor CXCR4 to migrate toward the lymphatic vessels, promoting a lymphatic microenvironment that supports tumor growth." (PMID 27806339, 2016). "The inhibition of CD11b+ cell recruitment through different approaches (i.e., CXCR-4 or SDF-1 inhibition) impairs tumor regrowth after single dose or fractionated RT in rat glioblastoma model and in murine prostate cancer model." (PMID 27064581, 2016). "In this model, CXCL12 secreted by BMDC attract CXCR4+ tumor cells to the pre-metastatic niche through the CXCL12–CXCR4 axis, aiding lung metastasis." (PMID 27136535, 2016). "BrdU staining of tumor sections showed significantly less proliferation in the CXCR4-mAb treated group compared to controls." (PMID 26848769, 2016). "The diagnostic accuracy of CXCR4 (71%) was similar to CRP (72%), much higher in comparison to CXCL12 (59%) and classical tumor markers (CEA: 49%, SCC-Ag: 46%), and increased to 77% in combined measurement with CRP." (PMID 27041792, 2016). "In this study, we explore the crucial role of CXCR4 in the invasion of tumor cells into the perivascular space by down-regulating the expression of CXCR4." (PMID 27863376, 2016). "We studied the potential of combining radiation therapy with targeting CXCR4 by knocking down the gene with shRNA within the tumor cells." (PMID 27863376, 2016). "Nearly 75% of TNBCs exhibit high levels of activated CXCR4 and this activation leads to tumor growth and correlates with formation of distant metastases." (PMID 26848769, 2016). "The growth of the primary tumor was reduced to a similar extent as with chemotherapy alone and metastasis formation was reduced to a similar extent as with CXCR4 inhibitor alone." (PMID 27835905, 2016). "The CXCL12/CXCR4 axis promotes tumor angiogenesis through multiple mechanisms that lead to the recruitment of CXCR4 positive vascular cells into tumor lesions and/or up-regulation of pro-angiogenic factors such as VEGF or other mediators [reviewed in Ref 30]." (PMID 27590504, 2016).
tumor (continued). "CXCR4-positive tumor cells can self-renew in a serum-free medium and display potent tumor-initiating capability." (PMID 26977157, 2016). "CXCR4 monoclonal antibody BMS-936564/MDX-1388 was previously demonstrated to induce apoptosis of hematologic tumor cells." (PMID 26954567, 2016). "We propose that GemOE tumor cells actively recruit MSCs to their vicinity through the signaling circuit “GemOEàHMGB1/RAGEàSDF1/ CXCR4." (PMID 26989079, 2016). "Our imaging and biodistribution studies, using whole tumors, show that uptake of 89Zr-CXCR4-mAb correlated with the levels of CXCR4 expression and therapeutic efficacy in the same tumor models." (PMID 26848769, 2016). "Radiation treatment increased apoptosis of CXCR4 downregulated tumor cells and prolonged median survival." (PMID 27863376, 2016). "CXC chemokine receptor 4 (CXCR4) plays a central role in tumor cell dissemination and metastasis development in more than 75% of all cancers." (PMID 27698675, 2016). "The interaction of SDF-1 and CXCR4 activates multiple signal transduction pathways in tumor cells, including PI3K/AKT and MAPK cascade, which are the two important pathways involved in cell survival and proliferation." (PMID 26954567, 2016). "Inhibition of CXCR4 reduced the growth of the primary tumor and suppressed metastasis formation, whereas chemotherapy failed to affect metastasis formation." (PMID 27835905, 2016). "There has been observed physical interaction between MIF and CXCR2, CXCR4, and CD74, although only CXCR4 is dominant receptor recognized by MIF in context of tumor homing." (PMID 27630452, 2016). "CXCL12/CXCR4 can directly influence the proliferation, migration and invasion of CXCR4-expressing tumor cells [reviewed in Ref 30]." (PMID 27590504, 2016). "For example, human induced pluripotent stem cells (iPS) with C-X-C chemokine receptor type 4 (CXCR4) have been used to load Au nanorods@SiO2@CXCR4 to achieve better tumor target migration, with CXCR4 used to increase loading." (PMID 27455336, 2016). "The control, CXCR4+/Lgr5-, Lgr5+/CXCR4- and Lgr5+/CXCR4+ Caco-2 and HT-29 cells were subjected to tumor sphere formation assay." (PMID 27835894, 2016). "Tumor cell invasion at the metastatic site was effectively reduced upon CXCR4 silencing, similar to the antagonist IT1t." (PMID 26744352, 2016). "The percentages of elevated results (diagnostic sensitivity) of CXCR4 (80%) were higher than those of CXCL12 (47%) and much higher than classical tumor markers—CEA (22%) and SCC-Ag (14%) as well as CRP (57%)." (PMID 27041792, 2016). "The CXCL12-CXCR4 chemotactic axis contributes to metastasis of numerous different human cancers and CXCR4 positive tumor cells are often detected at the leading edge of invasive tumors and in cancer stem cell populations." (PMID 27528222, 2016). "Here, we show that the cross communication between human tumor cells and zebrafish ligands is maintained, because zebrafish Cxcl12 activates human CXCR4 signaling in vitro and supports the formation of TNBC early metastases in vivo." (PMID 26744352, 2016). "Mice harboring SUM149 xenografts with a high expression of CXCR4 were treated with CXCR4-mAb and showed a significant reduction in tumor growth compared to control groups (vehicle and control-mAb)." (PMID 26848769, 2016). "Previously, numerous studies suggest importance of CXCR4-SDF-1 axis in tumor dissemination and cancer progression." (PMID 26896000, 2016). "Proliferation levels, detected by BrdU staining of excised tumor sections were also lower in CXCR4-mAb treated SUM149 mice." (PMID 26848769, 2016). "We found that these Lgr5+/CXCR4+ cells showed higher tumor formation potential in vitro and in vivo, were more resistant to chemotherapy, and had a greater tumor-generating ability after serial adoptive transplantation." (PMID 27835894, 2016).
tumor (continued). "Although other experiments are necessary to understand these findings, they seem to indicate, as previously reported, that the interaction of ECFCs through CXCR4 with SDF1 of tumor cells is strong enough." (PMID 27223433, 2016). "The SDF-1α/CXCR4 axis recruits MDSCs into the tumor microenvironment, where they function in immune evasion and exert tumor-promoting effects." (PMID 27996037, 2016). "In particular, ARI combination determines in both metastatic cells and CSCs strong inhibition of CXCR4, AKT and ERK1/2 pathways, all invasive signals associated with CRC progression, advanced tumor stage, lymphatic recurrence and poor prognosis." (PMID 27028869, 2016). "CXCR4-mAb treatment significantly reduced tumor growth in H1155 xenografts compared to controls (vehicle and control mAb) as early as 6 days following the start of treatment." (PMID 26848769, 2016). "Purified B effector cells kill tumor cells directly and such killing involves not only the Fas/FasL pathway, but also the CXCR4/CXCL12 pathway and perforin." (PMID 27528023, 2016). "If CXCR4 signaling is necessary for migration of tumor cells towards endothelial cells, downregulation of CXCR4 on tumor cells should inhibit their migration capability." (PMID 27863376, 2016). "CXCR4-expressing tumor cells preferentially colonize distant organs that secrete high levels of CXCL12, such as brain, lungs, lymph nodes, liver and bone marrow." (PMID 26744352, 2016). "Here, for the first time, we observed that the SDF-1/CXCR4 axis can be activated by the increased expression of EphA1 in HCC cells in the tumor microenvironment." (PMID 27066828, 2016). "In the present study, we discovered the novel regulation pathway of miR-126, which for the first time validated the mechanism of miR-126 acts as tumor suppressor, via regulation of the CXCR4 and RhoA signaling pathway both in vitro and in vivo." (PMID 27517626, 2016). "The contribution of epigenetic plasticity to CXCR4 heterogeneity is now worthy of investigation in the context of other tumors that display stem cell characteristics and in which CXCR4 positive cells contribute to tumor progression." (PMID 27528222, 2016). "On the other hand, the consistent stimulation of SDF-1 and down-regulation of USP33 gradually promote the degradation of CXCR4, which contribute to the lower CXCR4 level in liver metastases than primary tumor tissues." (PMID 27835898, 2016). "The number of CXCR4+CD49f− tumor cells was higher in spheroid-plug model than in classical model either in B16 or LLC tumors, while CXCR4+CD49f+ population was more abundant in spheroid-plug model only in B16 tumors." (PMID 26385771, 2016). "The process of MDSC migration is known to be driven by chemokine-chemokine receptor interactions, and indeed, our study showed the PAUF-induced upregulation of CXCR4, a chemokine receptor with a key role in the tumor cell-microenvironment crosstalk, on MDSCs." (PMID 27322081, 2016). "Blockade of the CXCL12 receptor CXCR4 with AMD3100 had significant anti-tumor activity and reversed the pro-angiogenic activity of Bay60-6583, but not its effects on MDSC accumulation and tumor-infiltrating Treg or CD8+T cells number." (PMID 27590504, 2016). "Two questions arise from these in vitro and in silico studies: do isoform gradients form in the tumor environment and what is the effect on CXCR4+ cell migration?" (PMID 25909600, 2015). "EGFR/CXCR4 coexpression was significantly associated with lymph node metastasis (P = 0.026), TNM stage (P = 0.048), and poor tumor differentiation (P = 0.004)." (PMID 25679210, 2015). "EGFR expression significantly correlated with tumor differentiation (P = 0.031), whereas CXCR4 expression significantly correlated with lymph node metastasis (P = 0.001)." (PMID 25679210, 2015). "Many studies have demonstrated a correlation between CXCR4 expression and tumor aggressiveness with regard to metastatic spread and limited patient overall survival (OS)." (PMID 25671300, 2015).
tumor (continued). "uPAR and CXCR4 expression is strongly up-regulated and represents a negative prognostic factor in various cancers; in fact, both receptors are involved in tumour progression, angiogenesis and metastasis formation 11,19,20,48." (PMID 26082201, 2015). "Abnormal expression of the chemokine receptor CXCR4 plays an essential role in tumor cell dissemination and disease progression." (PMID 25704881, 2015). "Conversely, some tumours showed heterogenous CXCR4 focal staining, which was clearly different from other cases with CXCR4 diffuse staining." (PMID 26161302, 2015). "Key to CXCR4 antagonism is the blockade of critical tumor-stromal interactions that occur within the specialized perivascular stem cell niche (PVN)." (PMID 26283963, 2015). "We identified a subpopulation of CMC cells showing human breast CSC features, including expression of specific markers (i.e. CD44, CXCR4), growth as mammospheres, and tumor-initiation in mice." (PMID 25884842, 2015). "Recent evidence suggests that CXCR4-mediated proliferation and metastasis of tumor cells is regulated by CXCR7 through its scavenging of chemokine CXCL12." (PMID 25884570, 2015). "The liver-to-tumor ratio of CXCR4-IR-783 reached a peak value (5.5 ± 0.7) at 4 hours and declined to 1.1 ± 0.2 at day 7 post injection." (PMID 26472699, 2015). "Because of its involvement in both metastasis and primary tumour growth, CXCR4 is an ideal target to investigate novel therapeutic interventions." (PMID 25753200, 2015). "The expression level of CXCR4 was much higher in the orthotopic tumor than in the metastasized cancer cells in vivo." (PMID 26083776, 2015). "The efficacy of AMD3100 as a CXCR4 antagonist has been proven in many studies for many different tumor types." (PMID 25671300, 2015). "An optimum dose gradient of CXCL12 conducted by the neurons and Schwann cells induces the chemotactic migration of CXCR4-bearing tumor cells toward the peripheral nerves, and simultaneously increases PCa cells metastasis and invasion, thereby establishing PNI." (PMID 25605248, 2015). "Recent studies showed that TGF-β2 and TGF-β1 can induce CXCR4 expression in several types of tumor cells including HNSCC cells and leukocytes, via TGF-β type I receptor-dependent non-Smad signaling pathways." (PMID 25504440, 2015). "Receptor-ligand SDF-1/CXCR4 affects downstream ligand molecule in bone marrow microenvironment, and also affects the tumor growth through adhesion." (PMID 26652601, 2015). "The anti-tumor activity of a CXCR4 antagonist has been shown in pre-clinical and animal tumor models, and several clinical studies on CXCR4 antagonists as chemosensitizer for treatment of patients with hematological and solid tumors are underway." (PMID 25613038, 2015). "For example, the CXCL12/CXCR4 axis plays an important role in tumor cell extravasation and tissue-specific homing." (PMID 25897429, 2015). "Although our findings do not sufficiently explain the mechanisms of the induction and exit of tumor dormancy, our findings suggest that CXCR4 facilitates tumor growth and serves as the switch of the tumor state from dormant to growing." (PMID 26083776, 2015). "Molecular studies have shown that SDF-1/CXCR4 axis promotes tumor cell survival, cell migration and metastasis by modulating numerous signaling pathways." (PMID 25775124, 2015). "Primary culture cells were therefore isolated from 4T1 tumours as they express CXCR4 in tumour microenvironment." (PMID 26592552, 2015). "Immunoblot analysis of lysates obtained from surgical samples of 13 HCC patients confirmed increases of CXCR4 expression in tumour relative to peritumour tissues." (PMID 26404566, 2015). "The CXCL12/CXCR4 axis also plays an important role in the PCa progression through tumor cell migration and invasion." (PMID 25605248, 2015).